INS (insulin)
Diseases named in the same sentence as INS in open-access papers (continued):
Sharing a sentence is not in itself a finding about the gene and the disease.
diabetes (continued). "Type 2 diabetes mellitus (T2DM) is a metabolic disorder primarily characterized by persistent hyperglycemia due to aberrant insulin secretion and/or islet dysfunction." (PMID 41586316, 2025). "Elevated insulin levels in diabetes can also enhance the effects of Insulin-like Growth Factor (IGF) and Vascular Endothelial Growth Factor (VEGF), promoting tumor cell proliferation." (PMID 39926430, 2025). "Among patients with diabetes, 169 patients (70.4%) were taking insulin, whereas only seven (2.9%) were on a glucagon-like peptide-1 (GLP-1) agonist." (PMID 40557020, 2025). "Among these, glucose remained the strongest predictor (AUC = 0.81), while BMI, insulin therapy, and longer diabetes duration provided additional predictive value." (PMID 41008733, 2025). "In summary, we present a non-invasive transdermal insulin delivery system that achieves in vivo hypoglycaemic efficacy comparable to subcutaneous injections for diabetes treatment, resulting from the efficient skin permeation of OP." (PMID 41261125, 2025). "The main types of diabetes mellitus are type 1 and type 2, and insulin therapy is an effective method to regulate abnormal blood glucose levels." (PMID 40292663, 2025). "Due to insulin’s singular role as the only hormone capable of lowering blood glucose, defects in β-cell function directly contribute to the onset of major forms of diabetes." (PMID 40136648, 2025). "A survey of 289 women with diabetes found that 50% of insulin pump users reported insulin pumps interfering with sex, and 75% disconnected their pump during sexual activity." (PMID 39302078, 2025). "Diabetes is a chronic metabolic disorder marked by high blood glucose levels resulting from inadequate insulin secretion or resistance to insulin action." (PMID 40260393, 2025). "Type 2 diabetes mellitus, a chronic metabolic disorder, arises from the development of peripheral insulin resistance coupled with inadequate insulin secretion from the pancreatic β-cells to maintain normal glucose homeostasis." (PMID 41377472, 2025). "Our findings confirm that longer diabetes duration is associated with a lower glycaemic response to GLP-1 RAs, probably due to declining beta cell function, as intact insulin secretion is necessary for a robust glycaemic response to this drug class." (PMID 40404820, 2025). "An elevated total blood cholesterol level has been observed in rats with STZ-induced diabetes and in insulin-resistant db/db mice." (PMID 40806520, 2025). "Subgroup analyses were performed across categories defined by age, gender, race, education, PIR, marital status, BMI, alcohol, smoking, diabetes, current insulin use, and hypertension." (PMID 40839683, 2025). "It seems that lowering PTP1B activity prevents fat and diabetes while simultaneously increasing the effect of insulin and leptin." (PMID 39950148, 2025). "The addition of thiamine is beneficial in reducing blood lipids in people with diabetes during intensive insulin therapy." (PMID 40299682, 2025). "The primary outcome was the change in insulin dosage, and secondary outcomes were disability-adjusted life years (DALYs) lost per 1,000 person-years by diabetes complication (micro- and macro-vascular)." (PMID 40245017, 2025). "These mice exhibit basal hyperinsulinemia, glucose intolerance, and reduced glucose-induced insulin secretion, closely resembling β-cells defects observed in human type 2 diabetes mellitus (T2DM)." (PMID 40422193, 2025). "For patients who require insulin to manage their diabetes, the appropriate administration of insulin is crucial." (PMID 40376558, 2025). "PTP1B, in addition to being a potential drug target for treating diabetes and obesity due to its role in downregulating insulin and leptin signalling, has also emerged as a potential therapeutic target for breast cancer treatment." (PMID 41286812, 2025).
diabetes (continued). "Diabetes and liver health are closely interconnected, with diabetes-related hepatic complications such as NAFLD (non-alcoholic fatty liver disease) also associated with disturbances in hepatic metabolism and insulin signaling." (PMID 41162165, 2025). "Diabetes duration was 86 ± 49 days, 25(OH)D level 31.52 ± 10.24 ng/mL, fasting C-peptide 0.31 ± 0.15 pmol/mL, and daily insulin dose 0.35 ± 0.22 units/kg/day (n = 18)." (PMID 40276675, 2025). "In clinical practice, diabetes treatment using insulin with high affinity for IGF-I receptors improves the lipid profile, increases insulin sensitivity, and enhances glucose metabolism." (PMID 41514592, 2025). "Diabetes mellitus (DM) is a metabolic disease characterized by persistent hyperglycemia, resulting from defects in insulin secretion or impaired insulin action." (PMID 40943666, 2025). "Given insulin’s critical role in diabetes management, extensive efforts have been made to improve purification and develop formulations that better align with patients’ physiological needs." (PMID 41531706, 2025). "In rats with STZ-induced diabetes, blood insulin levels were significantly reduced (hypoinsulinemia) compared to normal values." (PMID 40806520, 2025). "Type 1 diabetes mellitus (T1DM) is characterized by hyperglycemia resulting from defects in insulin secretion." (PMID 41471783, 2025). "The trial seeks to restore glucose control by promoting insulin production, a significant innovation in diabetes treatment." (PMID 39858654, 2025). "Suppression of RNF213 expression reduced ER stress levels and improves insulin sensitivity, suggesting a protective role against the development of diabetes." (PMID 41234236, 2025). "Twenty-eight (30.1%) patients had diabetes, most of whom were treated with oral antidiabetic drugs (87.5%), and only 33.3% were treated with insulin." (PMID 40867136, 2025). "Methanolic extracts from chaya have been found to boost the activity of beta cells and enhance insulin secretion, helping to regulate blood glucose levels in rats with diabetes induced by streptozotocin (STZ)." (PMID 41011114, 2025). "The duration of diabetes was mainly reported as one to five years (n = 108, 36%), with common treatments including insulin injections (n = 114, 38%) and oral medications (n = 100, 33%)." (PMID 41035812, 2025). "Combined aerobic and resistance training elicits complementary physiological adaptations that contribute to significant improvements in insulin sensitivity, glycemic control, and HbA1c levels in individuals with type 2 diabetes mellitus." (PMID 41295324, 2025). "Type 2 diabetes mellitus (T2DM) is a chronic metabolic disease characterized by hyperglycemia, caused by defects in insulin secretion, insulin action, or both." (PMID 40492727, 2025). "Diabetes self-management is critical, particularly in insulin-treated patients and it is largely based on glucose monitoring, which allows recording glucose levels to make informed decisions with respect to meals, exercise, and other daily-life activities." (PMID 40497316, 2025). "The insulin-treated gestational diabetes group was also characterized by a recent family history of diabetes compared to mothers of the control or diet-controlled gestational diabetes group." (PMID 39384641, 2025). "Primary human ductal progenitor-like cells derived from donated pancreas have the potential to serve as a source of therapeutic insulin-producing beta cells for the treatment of diabetes." (PMID 40424137, 2025). "Diabetes mellitus is a common complication of CS, which is the result of the development of insulin resistance in the body as well as impaired insulin secretion induced by glucocorticoid overdose." (PMID 41158634, 2025). "Diabetes mellitus comprises a group of metabolic disorders characterized by hyperglycemia resulting from impaired insulin secretion or activity." (PMID 41463606, 2025).
diabetes (continued). "Early relapse has been associated with a number of clinical variables, including poor preoperative diabetes control, longer duration of the disease, insulin requirement for glucose control, and decreased pancreatic beta cell reserve." (PMID 40358866, 2025). "This long-acting basal insulin analog, used to manage blood glucose levels in individuals with diabetes mellitus, provides consistent and prolonged blood glucose control, making it a crucial component of diabetes management." (PMID 40190894, 2025). "Nanotechnology is redefining diabetes management by enabling non-invasive glucose monitoring, targeted insulin delivery, and next-generation cell- and gene-based therapies for Type 1 diabetes (T1DM)." (PMID 41404505, 2025). "In Type I Diabetes Mellitus (TIDM), the pancreas fails to produce insulin; consequently, its treatment involves insulin administration and accounts for 10% of all diabetes cases." (PMID 40601679, 2025). "Impaired insulin signaling was associated with PACS in patients who also have an increased risk of diabetes and diabetes‐related complications." (PMID 41190280, 2025). "The main strength of the present study lies in its assessment of the impact of insulin pump therapy on blood glucose control and acute diabetes complications." (PMID 41146752, 2025). "In diabetes, elevated blood glucose levels lead to the overproduction of reactive oxygen species (ROS), which impairs insulin signaling, damages pancreatic β-cells, and contributes to the development of vascular complications." (PMID 41155632, 2025). "Other promising developments include albumin–insulin conjugates for diabetes management, which leverage albumin’s prolonged half-life to achieve sustained glucose control, as well as albumin-bound photosensitizers for photodynamic cancer therapy." (PMID 40699702, 2025). "Diabetes mellitus (DM) is a serious metabolic disorder and public health problem globally characterized by hyperglycemia associated with inadequate insulin production and/or ineffectiveness of produced insulin." (PMID 41497486, 2025). "This study aimed to evaluate the efficacy and safety of DWP16001, a selective sodium-glucose cotransporter 2 inhibitor, as an adjunct to insulin therapy for client-owned dogs with diabetes mellitus." (PMID 40796840, 2025). "The development of once-weekly basal insulin analogues, such as insulin icodec and efsitora alfa, represents a promising strategy to reduce injection burden and improve adherence in diabetes management." (PMID 40937414, 2025). "In this study, we have shown that socioeconomic deprivation has a significant impact on access to diabetes technology, specifically insulin-delivery pumps." (PMID 40718276, 2025). "MBS offers significant clinical benefits, particularly in the management of diabetes, as it improves insulin sensitivity and beta-cell function, often leading to diabetes resolution." (PMID 41155711, 2025). "In diabetes advanced age, marital status, the requirement for insulin therapy, high HbA1c levels, longer disease duration, and the presence of complications were significantly associated with severe depression." (PMID 40333937, 2025). "Remarkably, in individuals with obesity and diabetes, insulin’s vasoconstrictive and proatherogenic effects tend to dominate." (PMID 40725728, 2025). "Type 2 diabetes mellitus (T2D) and ulcerative colitis (UC) often coexist as comorbidities characterized by chronic inflammation, microbial imbalance, and insulin dysregulation, yet effective therapies remain limited." (PMID 41155631, 2025). "In many regions, including Asia, Africa, South America, and Eastern Europe, access to advanced diabetes technologies such as insulin pumps and CGM is limited, though the availability of CGM is gradually increasing." (PMID 41142656, 2025).
diabetes (continued). "Insulin resistance is characterized by reduced sensitivity and responsiveness to insulin, which is at the core of various health problems, including diabetes, cardiovascular disease, and cognitive decline." (PMID 40800025, 2025). "The incident diabetes groups showed a decline in insulin sensitivity and β-cell function, resulting in a decrease in the disposition indices over time." (PMID 40361840, 2025). "There is ample evidence that insulin and related hormones play an important role in development and metabolism, and that abnormalities in insulin secretion and uptake can lead to hyperglycaemia and diabetes." (PMID 40699855, 2025). "Insulin in pharmacology focus on its role as a crucial hormone in glucose homeostasis and its therapeutic use in managing diabetes." (PMID 40771585, 2025). "Another study used saRNAs to differentiate adult human CD34+ cells into insulin-secreting cells to treat diabetes." (PMID 40985895, 2025). "Both subtypes share characteristics similar to type 1 diabetes mellitus, including lower body mass index, higher rates of diabetic ketoacidosis, and faster progression to insulin therapy." (PMID 41302503, 2025). "This miniaturized, high-resolution magnetic insulin pump is anticipated to substantially benefit people with diabetes by improving portability, precision, and cost efficiency." (PMID 41728094, 2025). "The sitagliptin and bedtime NPH insulin groups were comparable in age, body mass index, diabetes duration, and baseline metabolic variables." (PMID 41282288, 2025). "Understanding the impact of continuous glucose monitoring (CGM) vs self-monitoring of blood glucose (SMBG) is important for treating older adults with Alzheimer disease and related dementias (ADRD) and diabetes that is treated with insulin." (PMID 41329488, 2025). "Sarcopenia among individuals with diabetes presents a multifaceted challenge and is influenced by various factors such as insulin resistance, inflammation, oxidative stress, and hormonal changes." (PMID 40075050, 2025). "Other studies reported several factors associated with insulin-self-administration practice, including gender, education, occupation, duration of insulin therapy, and duration of diabetes." (PMID 40471961, 2025). "This is similar to the vaccine uptake of 54–56% reported in people with chronic respiratory disease, chronic kidney disease, and diabetes requiring insulin or oral hypoglycaemic medication." (PMID 38479823, 2025). "The reliance on insulin-based therapy in dogs and cats with diabetes reflects biological factors, such as species-specific pharmacokinetics, and regulatory limitations, as few antidiabetic agents received formal approval for veterinary use." (PMID 41012437, 2025). "Insulin is a life-saving medication for individuals with type 1 diabetes mellitus and is also essential for some patients with type 2 diabetes mellitus who require daily injections to maintain glycemic control." (PMID 40465749, 2025). "Fasting insulin, C-reactive protein, and fasting glucose—typically elevated in diabetes—also showed decreases, likely reflecting vitamin D’s protective effects on pancreatic β cells." (PMID 41010515, 2025). "More than 90% of cases are type 2 diabetes mellitus (T2DM), associated with impaired insulin secretion, reduced tissue sensitivity to insulin, and insufficient compensatory insulin release." (PMID 41149433, 2025). "The pancreas plays a crucial role in diabetes because it produces the hormone insulin, which is essential for regulating blood glucose levels." (PMID 40760015, 2025). "Recent advancements in MN applications have shown their effectiveness in delivering insulin for diabetes management, offering a viable alternative to traditional subcutaneous injections." (PMID 40428648, 2025). "The CA treatment group also had significantly higher insulin levels than the diabetic control group, supporting CA’s effectiveness in addressing diabetes-related changes." (PMID 40872532, 2025).
diabetes (continued). "In people with diabetes, hypoglycaemia is the consequence of the interaction between relative insulin excess from treatment and compromised physiological defences against falling plasma glucose." (PMID 39996361, 2025). "In a recent study of 161 patients with MIDD 77.45% were using insulin with mean time from diabetes diagnosis to insulin initiation of 4.15 years." (PMID 40471292, 2025). "These components regulate the abundance of gut microbiota, improve glucose metabolism, and enhance insulin sensitivity, thereby providing auxiliary treatment for diabetes." (PMID 40177494, 2025). "Dipeptidyl peptidase-4 (DPP-4) inhibitors have been widely applied to treat diabetes via inhibiting degradation of GLP-1 to regulate insulin secretion." (PMID 40810069, 2025). "This program addressed not only insulin pump self-management but also emotional and motivational aspects of life with diabetes." (PMID 39172172, 2025). "Diabetes is a disease characterized by hyperglycemia resulting from defects in insulin secretion, insulin resistance, or both." (PMID 39950148, 2025). "This lack of documentation raised concerns regarding the clinical reasoning behind withdrawing insulin in a patient with longstanding diabetes." (PMID 40376133, 2025). "Animal studies have also demonstrated that antibiotic treatment alters intestinal microbiota, reduces tissue inflammation, improves insulin signaling, and enhances glucose metabolism in mice prone to obesity and diabetes." (PMID 40533417, 2025). "In the meanwhile, diabetes, a chronic metabolic disorder due to impaired insulin secretion or action, is one of the significant public health concerns worldwide." (PMID 41002316, 2025). "Multivariable models controlled for age, sex, race, marital status, rurality, diabetes duration, social support, and insulin use." (PMID 40029547, 2025). "Metformin (which lowers glucose and insulin levels), sulfonylureas (which promotes insulin secretion from the pancreas), and insulin analogs (such as glargine insulin) are therapeutic options for diabetes." (PMID 39948335, 2025). "Diabetes mellitus (DM) is a globally prevalent metabolic disorder characterized by chronic hyperglycemia resulting from impaired insulin secretion, insulin resistance, or both." (PMID 41464936, 2025). "Results showed significant reductions in HbA1c, weight and daily insulin doses with both doses of sotagliflozin, along with improvements in the Diabetes Treatment Satisfaction Questionnaire (DTSQ) scores." (PMID 40130476, 2025). "Mitochondrial diabetes (MD), a rare form of monogenic diabetes, is primarily characterized by insulin secretion failure in pancreatic β-cells due to impaired mitochondrial ATP production." (PMID 39835172, 2025). "In fact, together with improvements in a wide range of chemosensory parameters, diabetes-related markers (fasting glucose, insulin, and HOMA) underwent significant improvements or a trend for amelioration." (PMID 39970875, 2025). "For patients with type 2 diabetes mellitus, probiotic supplementation improved glycemic control, insulin sensitivity, and inflammatory markers, highlighting their role in metabolic regulation." (PMID 41178959, 2025). "A German clinic also demonstrated that a cohort of 80 insulin users collected a total of 23,707 diabetes-related disposables over a period of three months, estimated to be 1.2 billion discarded items annually." (PMID 41332366, 2025). "Diabetes mellitus represents a growing global health challenge characterized by insufficient insulin secretion from the pancreas or the inability of produced insulin to bind to its target receptors." (PMID 40823021, 2025). "PTP1B, is a key negative regulator of insulin signaling and its inhibition can target both diabetes and obesity." (PMID 40686811, 2025). "Intensive insulin therapy can control blood glucose levels and reduce or prevent diabetes-related complications." (PMID 40428118, 2025).